ICAM1 (intercellular adhesion molecule 1)
Diseases named in the same sentence as ICAM1 in open-access papers (continued):
Sharing a sentence is not in itself a finding about the gene and the disease.
colitis (continued). "Naringenin abrogated experimental colitis by downregulating proinflammatory mediators like iNOS, ICAM-1, monocyte chemoattractant protein-1, COX-2, TNF-α, and IL-6." (PMID 27635116, 2016). "Many of the inflammatory cytokines attenuated by FFAR2 and FFAR3, including C5, CCL1, CCL2, GM-CSF, IL-1α, IL-1β, ICAM-1 and TNF, are associated with colitis." (PMID 27667443, 2016). "Reduction in ICAM-1 expression would explain previous results using the mouse colitis model in which plasma protein supplementation reduced leukocyte infiltration into the colon mucosa." (PMID 27782068, 2016). "Intercellular adhesion molecule-1 (ICAM-1) has been shown to be upregulated in inflammatory regions of the colon, which occurs in conditions causing colitis and in IBD." (PMID 24959147, 2014). "Blockade of PARP inhibits intercellular adhesion molecule 1 (ICAM-1) or cyclooxygenase-2 expression, neutrophil recruitment, oxidant generation, and mucosal injury in murine colitis." (PMID 20204057, 2009). "In this perspective, experiments using a loxed ICAM-1 animal crossed with inducible Cre under a glial promotor in a Winnie phenotype would be necessary in particular to assess the role of glial ICAM-1 in the formation of plexitis and its possible contribution to the development of colitis." (PMID 38428588, 2024). "Thus, the previously demonstrated potent inhibition of ICAM-1–Mac-1 interaction by DARPin F7 suggests a beneficial effect in DSS colitis." (PMID 37511839, 2023). "Furthermore, there is clear evidence for the crucial role of ICAM-1 in the pathogenesis of DSS colitis." (PMID 37511839, 2023). "Following this, ALA supplementation in TNBS-colitis rats inhibited the protein expression of intercellular adhesion molecule-1 (ICAM-1), vascular cell adhesion molecule (VCAM-1), and vascular endothelial growth factor receptor-2 (VEGFR-2) that mediates leukocyte recruitment and angiogenesis in IBD." (PMID 35399093, 2022). "Thus, a significant increase in mRNA of TNF, IL-6, IL-1β, and ICAM-1 genes in the proximal colon in mice with DSS-induced colitis compared with control mice." (PMID 36359839, 2022). "Anti-ICAM1 monoclonal antibody prophylactic treatment had been reported that could alleviate symptoms in a dextran sulfate sodium (DSS)-induced colitis model." (PMID 36248794, 2022). "The downregulation in the expression of the MIP-2 and MCP-1 chemokines, and of the ICAM-1 adhesion molecule by the HEBP improved colonic inflammation in both experimental colitis models, thus resulting in reduced migration and penetration of inflammatory cells into the intestinal mucosa." (PMID 32848723, 2020). "In another studies made in our laboratory we demonstrated, in a murine model of colitis, that cashew nuts treatment, was able to alleviate the clinical signs of colon damage as well as oxidative stress, inflammation, and iNOS, ICAM-1, and P-selectin expressions." (PMID 32722199, 2020). "On the other hand, a relevant report established that VCAM-1 plays a central role in leukocyte recruitment in colitis and blockade of this adhesion molecule has higher therapeutic effect than immune neutralization of ICAM-1 or MAdCAM-1 in colitis experimental model." (PMID 22073270, 2011). "For instance, treatment with geraniol significantly opposed the TNBS-induced colitis effects on the inflammatory parameters, including NFκB, PGE2, IL-1β, ICAM-1, and MPO." (PMID 36009287, 2022). "In the DSS-colitis mice, supplementation of CPn or citrus residues (from juice extraction) decreased the expression of pro-inflammatory genes (TNF-α, IL-1β/-16, iNOS, ICAM-1) and colon weight/length ratio." (PMID 35399093, 2022). "Plumericin reduced the activity of myeloperoxidase, inhibited the expression of ICAM-1, P-selectin, and the formation of PAR, and reduced apoptosis parameters in mice colitis induced by DNBS." (PMID 33445622, 2021).
colitis (continued). "This is in line with previous reports and with our analysis showing an increase in ICAM-1 and MAdCAM-1 levels on endothelial cells throughout DSS-induced colitis." (PMID 33932356, 2021). "The mRNA expression of IL-1β, IL-18, IL-6, TNF-α, IFN-γ, ICAM-1, and VCAM-1 was markedly (all p < 0.01) up-regulated in DSS-induced colitis group, while the IL-10 expression was significantly (p < 0.01) down-regulated." (PMID 33859564, 2021). "Studies have reported that the elevated levels of adhesion molecules (ICAM-1 and VCAM-1) were founded in the DSS-induced colitis mice." (PMID 33859564, 2021). "Because the colonic Treg cells have been shown to inhibit ICAM-1 expression and macrophage infiltration in the colon in DSS colitis, it is tempting to speculate the retained colonic Treg cells in KI mice may be related to the susceptibility to DSS-induced innate colitis." (PMID 32522281, 2020). "mRNA expression of iNOS, ICAM-1, MCP-1, COX-2, TNF-α and IL-1β was remarkably induced in the colonic tissues of TNBS-colitis mice." (PMID 29180692, 2017). "The expressions of ICAM-1, IL-1β, IL-16, CXCL10, MCP-1, CXCL9, CXCL12, and TIMP-1 were greatly reduced in MSC-EX-treated colitis group compared with those in the PBS-treated colitis group." (PMID 28842625, 2017). "According to our data, baicalein effectively inhibited the mRNA expression of iNOS, ICAM-1, COX-2, MCP-1, TNF-α and IL-1β in the colon of TNBS-colitis mice." (PMID 29180692, 2017). "Another study demonstrated that induction of colitis in rats by TNBS is followed by up-regulation of endothelial VCAM-1, and suggests that VCAM-1 and constitutive ICAM-1 are major determinants of leukocyte recruitment to the inflamed intestine." (PMID 22073270, 2011). "In contrast to our results, other studies indicate an anti-inflammatory role for 17 HDHA, with negative correlations observed with IL-1β and other cytokines and adhesion molecules such as TNF-α, MIP-2, CXCL1/KC, VCAM-1, ICAM-1, and LFA-1 in an animal model of colitis." (PMID 41009650, 2025). "The authors found that ICAM-1 and, to a greater degree, VCAM-1 antibody blockade significantly attenuated leukocyte adhesion to colonic venules in experimental rat models of 2,4,6-trinitrobenzene sulphonic acid (TNBS)-induced colitis." (PMID 40095109, 2025). "Similarly, the intercellular adhesion molecule 1 (ICAM-1) expression, a molecule whose upregulation strongly correlates with increased DSS-colitis symptoms, was significantly increased in the DSS and EcN groups, compared to the EcN aldh group." (PMID 39080343, 2024). "In a rat model of AA-induced colitis, phloretin, administered orally either before or after induction of colitis (50 mg/kg), effectively reduced plasma ALP and LDH levels, inflammatory markers (MPO, NO, eosinophil peroxidase), and colon ICAM-1 gene expression." (PMID 39494333, 2024). "In this study, VCAM-1 blockade had a larger effect than ICAM-1 blockade on leukocyte adhesion, indicating ICAM-1 is not the only adhesion molecule with a role in driving inflammation in colitis." (PMID 37237555, 2023). "Baicalin ameliorated TNBS-induced colitis injury by suppressing TLR4 signaling in a concentration-dependent manner, inhibiting NF-κB activation and limiting the inflammatory response, such as ICAM-1, MCP-1, Cox-2, TNF-α, IL-1β and IL-6." (PMID 35484567, 2022). "VCAM-1 antagonists proved superior to ICAM-1 and MAdCAM-1 blockade in the murine model of DSS colitis, and the monoclonal anti-α4 integrin antibody natalizumab has been successfully used for blockade of VCAM-1-dependent leukocyte trafficking in patients with active CD." (PMID 34017333, 2021). "ICAM-1 has been shown to interact with target cells during cytotoxic T cell and natural killer cell-mediated damage, and ICAM-1 has also been shown to prevent and reverse dextran sulfate sodium-induced colitis in mice." (PMID 34630738, 2021).
colitis (continued). "Moreover, total loss of α4β7 function has been shown to lead to colonic Treg depletion, which promotes ICAM-1 expression and macrophage infiltration into the colon and exacerbates DSS-induced colitis." (PMID 32522281, 2020). "In the same study, chronic administration of anti-VCAM-1 antibody, but not anti-ICAM-1 or anti-MAdCAM-1, resulted in significant attenuation of colitis in terms of disease activity index, colon length, ratio of colon weight to length, and myeloperoxidase activity." (PMID 22073270, 2011). "Interestingly, the authors found that simultaneous ICAM-1/VCAM-1 blockade did not further inhibit leukocyte adhesion compared to VCAM-1 blockade alone, implicating VCAM-1 as an optimal adhesion target for selective inhibition of colitis-associated leukocyte recruitment." (PMID 40095109, 2025).
type 2 diabetes (69 papers, 2007 to 2025). "It would be advisable that in the future attention should be paid to the relationship between other ICAM-1 polymorphisms and DR in type 2 diabetes." (PMID 30419874, 2018). "The current mete-analytic review was conducted to verify the genetic contribution of a common SNP, rs5498 in the ICAM-1 gene to retinopathy risk in type 2 diabetes." (PMID 30419874, 2018). "In the present study, we aimed to provide a quantitative evaluation of the association between DR in type 2 diabetes and the ICAM-1 rs5498 polymorphism." (PMID 30419874, 2018). "Combining published data from nine studies involving 3192 participants, this is the largest meta-analysis on the relationship between the ICAM-1 rs5498 polymorphism and retinopathy in type 2 diabetes." (PMID 30419874, 2018). "Other GWAS studies also identified ABO as a locus for low-density lipoprotein (LDL-C), type-2 diabetes, inflammatory risk biomarkers E-selectin, P-selectin, and sol-ICAM1." (PMID 24475106, 2014). "Additionally, new markers for oxidative stress and EC dysfunction were associated with type II diabetes (T2D), including F2-isoprostances, intercellular adhesion molecule-1 (ICAM-1), and E-selectin." (PMID 37174741, 2023). "In addition, intercellular adhesion molecule-1 (ICAM-1) levels are increased in serum associated with increasing type-2 diabetes." (PMID 34045956, 2021). "In addition, an ICAM-1 deficient db/db mouse model of type 2 diabetes showed decreased leukocyte infiltration, reduced glomerular hypertrophy, decreased albuminuria, and decreased tubulo-interstitial fibrosis." (PMID 30587209, 2018). "Elevated levels of pro-inflammatory factors, including TNF-α, IL-6, and ICAM-1, can have a predictive role for the development of diabetic neuropathy in type 2 diabetic patients." (PMID 39596058, 2024). "The increased levels of IL-6 and Intercellular Adhesion Molecule 1 (ICAM-1) have been proposed to be the mediators between poor sleep quality and the development of cardiovascular complications in type 2 diabetic patients." (PMID 37571368, 2023). "ADM has been shown to induce the expression of VCAM-1 and ICAM-1 on human umbilical vein endothelial cells and was associated with an increase in VCAM-1 and ICAM-1 expression in type 2 diabetes patients." (PMID 36362188, 2022). "Type 2 diabetes-induced liver damage is almost always accompanied by severe hepatic inflammation characterized by the expression increases of ICAM-1, TNF-α, and PAI-1." (PMID 34307690, 2021). "ICAM-1 and VCAM-1 are relevant to chronic inflammatory processes, with an increased risk for type 2 diabetes (T2DM) and cardiovascular diseases (CVD)." (PMID 32795274, 2020). "The beneficial effects of intra-gastric administration of apigenin to type 2 diabetic (T2D) rats were expressed as decreases of the blood glucose concentration and ICAM-1 levels and improved impaired glucose tolerance." (PMID 32326376, 2020). "Another sign of impaired endothelial function is elevated levels of circulating soluble iCAM-1 and vCAM-1 in blood, which is partially reflected in our study: the vCAM-1 level was elevated in obese patients with type 2 diabetes." (PMID 30871567, 2019). "Levels of VEGF, IL-6, IL-8, inducible protein-10 (IP-10), intercellular adhesion molecule 1 (ICAM-1), and monocyte chemotactic protein 1 (MCP-1) are associated with macular edema in type 2 diabetic patients." (PMID 31635036, 2019). "Further, metformin was associated with decreased serum soluble vascular cell-adhesion molecule-1 (sVCAM-1) and soluble ICAM-1 levels in patients with type 2 diabetes during a follow up of 4 years." (PMID 29513760, 2018). "Increased plasma levels of nitrotyrosine, another reactive nitrogen species, in type 2 diabetic patients were observed to have a significant positive correlations with plasma levels of ICAM-1." (PMID 27847626, 2016).
type 2 diabetes (continued). "There is little evidence about s-ICAM role in GDM; most studies reveal the significance of s-ICAM-1 as predictor of type 2 diabetes in women with previous GDM." (PMID 26981539, 2016). "Sympathetic blockade by administration of an alpha-1- and beta-adrenoreceptor antagonist attenuated the expression of ICAM-1, and leukocyte-endothelium interaction in a rat model of type 2 diabetes." (PMID 24708631, 2014). "Real-time PCR and western blotting assays revealed that type 2 diabetes significantly up-regulated the expression levels of inflammatory factors (ICAM-1, TNF-α and PAI-1) and nitrosative damage markers (3-NT and MDA) in the kidney." (PMID 24651118, 2014). "It has been demonstrated that patients with Type 2 diabetes exhibit an attenuated upregulation of ICAM-1, VCAM-1, and E-selectin after various stimuli such as LPS." (PMID 24750819, 2014). "Increased kidney expression of intercellular adhesion molecule-1 (ICAM-1) has been noted in models of type 1 and type 2 diabetes." (PMID 22969168, 2012). "Furthermore, Elgarf et al27 indicated that oral consumption of 1.8 g/day N. sativa oil for 12 weeks remarkably decreased serum ICAM-1 levels in patients with type 2 diabetes compared with the diabetic control subjects." (PMID 40365513, 2025). "However, it fails to prevent mesangial expansion, which is attributed to a reduction in intercellular adhesion molecule 1 (ICAM-1) expression by tubular epithelial cells in type 2 diabetic db/db mice." (PMID 38671903, 2024). "Our results showed a lack of association between the ICAM-1 rs5498 polymorphism and risk of retinopathy in type 2 diabetes." (PMID 30419874, 2018). "Longer-term clinical trials might be required to verify the effect of teneligliptin on the expression of ICAM-1/VCAM-1 in type 2 diabetes patients." (PMID 27184495, 2016). "In contrast to healthy subjects, most regular consumption trials with patients suffering from type 2 diabetes or impaired glucose tolerance found lower concentrations of ICAM-1 and P-selectin in serum or plasma and a reduced expression of VLA-4, CD36, and CD40 on monocytes." (PMID 27240397, 2016). "While ICAM-1 levels and its polymorphisms appear linked to the development of nephropathy, the levels of modified LDL in IC and the levels of fibroblast growth factor have predictive value for cardiovascular disease in type 1 and type 2 diabetes." (PMID 25126086, 2014). "A soluble form of ICAM-1 has been described as increased in patients with type 2 diabetes and DN." (PMID 22969168, 2012). "In order to explore in more depth the inflammatory process that occurs in type 2 diabetes, we measured the levels of inflammation markers TNF-α, ICAM-1 and MPO in serum, and compared the leukocyte–endothelium interactions in type 2 diabetic participants with those in healthy participants." (PMID 38981930, 2024). "Another study indicated that intramuscular administration 300000 IU vitamin D supplement in type 2 diabetes (T2D) patients with ischemic heart disease had no significant changes in the levels of ICAM-1 and VCAM-1." (PMID 33224249, 2020). "ICAM-1 and VICAM-1 have been reported to predict the development of type 2 diabetes in women irrespective of other known risk factors including abdominal obesity or CRP levels as a marker of inflammation." (PMID 26981539, 2016). "Consistent with this observational data, we previously found that almonds decreased IL-6 and CRP, and TNF-α in Chinese patients with type 2 diabetes but did not affect ICAM-1 or VCAM-1." (PMID 26080804, 2015). "Several studies have shown that circulating levels of ICAM-1, E-selectin, tPA:Ag, vWF:Ag, and PAI-1:Ag have been linked to the risk of type 2 diabetes in populations without the previous history of GDM." (PMID 22577379, 2012).